GLS (glutaminase)
Diseases named in the same sentence as GLS in open-access papers (continued):
Sharing a sentence is not in itself a finding about the gene and the disease.
psoriasis (8 papers, 2017 to 2023). An autoimmune condition characterized by red, well-delineated plaques with silvery scales that are usually on the extensor surfaces and scalp. "As we observed in cell culture synthetic lethality between miR‐31 expression and GLS inhibition by CB‐839, we tested the effect of CB‐839 treatment in this model for psoriasis." (PMID 36855912, 2023). "The presence of celiac disease-specific antibodies against gliadin, reticulin, glutaminase and smooth muscle endomysium was also reported in subjects with psoriasis and other autoimmune and inflammatory conditions, such as SLE, RA and Sjögren’s syndrome." (PMID 28905102, 2017). "Recently, Xia and colleagues found that Glutaminase 1(GLS1)-mediated glutaminolysis was aberrantly activated in psoriasis patients, as indicated by elevated mRNA and protein levels in both immune cells and keratinocytes, contributing to the pathogenesis of psoriasis." (PMID 35075118, 2022). "Because of the thinning or disappearance of the granular layer at psoriasis lesions, the spinous layer may prematurely express the products (such as fatty acid-binding protein, filaggrin, corneodesmosin, glutaminase, involucrin, and loricrin) normally expressed in the granular layer." (PMID 33967781, 2021). "Consequently, breaking the cross‐talk between T cells and keratinocytes by inhibiting glutaminase (GLS), a key enzyme in glutamine metabolism, or SLC1A3, a key transporter of aspartate uptake, alleviates psoriasis in a mouse model." (PMID 36855912, 2023). "Glutaminolysis, an abnormal activation mediated by glutaminase 1 (GLS1), promotes Th17 and γδ T17 (IL-17A-producing γδ T cell) cell differentiation by enhancing histone H3 acetylation of the IL17A promoter, leading to an immune imbalance and the development of psoriasis." (PMID 37443834, 2023).
cyst (7 papers, 2018 to 2025). A sac-like closed membranous structure that may be empty or contain fluid or amorphous material. "BxPC3 cells, at least partially, depended on anaplerosis through glutamine as combining cyst(e)inase with CB-839, a glutaminase (GLS) inhibitor, produced a mild combinatorial inhibition of cell survival." (PMID 31231686, 2019). "In addition, treatment of Pkd1-mutant mice with a glutaminase inhibitor in utero (by administration to the mother) and postnatally (up to P10) slowed cyst progression." (PMID 33758231, 2021). "Indeed, treatment with the GLS inhibitors CB-839 resulted in a certain degree of reduction of cyst burden in two models of Pkd1 mutants, while it failed to improve the phenotype in a third one22." (PMID 30480096, 2018). "In ADPKD, treatment with a glutaminase inhibitor in PKD1-mutant mice, both in utero and postnatally, resulted in slowed cyst progression, highlighting the potential therapeutic benefit of targeting glutamine metabolism in ADPKD." (PMID 40722668, 2025). "Glutaminase (GLS) inhibitors, such as telaglenastat (CB-839), can force cyst cells into glutamine starvation." (PMID 40722668, 2025). "During glutaminolysis the enzyme glutaminase (GLS) converts glutamine to glutamate then converted to a TCA cycle intermediate, alpha-ketoglutarate to generate ATP for cyst growth." (PMID 36876046, 2023).
diabetes (7 papers, 2020 to 2025). "In the past, metformin has been proven to inhibit GLS (glutaminase) activity and ammonia accumulation, thereby reducing the risk of some diseases in patients with type 2 diabetes mellitus." (PMID 33157911, 2020). "In diabetes, the genes associated with lipid and glucose metabolism, such as PPARγ, IRS1 and IRS2 were genetic risk factors, and hepatic glutaminase mRNA was abundant during diabetes." (PMID 33466498, 2021). "Of note, recent studies showed that the diabetes drug metformin substantially suppressed MYC expression, reduced GLS activity, and inhibited autophagy in tumor cells 45-47." (PMID 34335968, 2021).
kidney cancer (7 papers, 2017 to 2023). Primary or metastatic malignant neoplasm involving the kidney. "The methylation level of the promoter of the GLS gene was found to be decreased in different types of cancer, including bladder, breast, colon, esophageal, head-and-neck, and kidney cancer." (PMID 30871151, 2019). "GLS was selectively amplified only in the presence of the VHL mutation (HI-HI Boolean implication), GLS amplification resulted in increased expression of GLS, and GLS was differentially overexpressed in VHL-mutant compared to VHL-wild-type kidney cancer." (PMID 28561042, 2017).
thyroid cancer (7 papers, 2016 to 2025). "Here, we found that thyroid cancer cells were more sensitive to DON than to the selective GLS inhibitor BPTES." (PMID 38386265, 2024). "Our data, taken together, demonstrate that STAG2 inactivation reprograms glutamine metabolism of BRAF-mutant thyroid cancer cells, thereby improving their cellular response to glutaminase inhibitor." (PMID 37479689, 2023). "Surprisingly, we find that STAG2 knockdown makes BRAF-mutant thyroid cancer cells more sensitive to glutamine deprivation or glutaminase inhibitor via the ERK/AKT/GSK3β/c-Myc feedback axis." (PMID 37479689, 2023). "We next treated thyroid cancer cells with glutaminase inhibitor BPTES to evaluate its effect on cell proliferation." (PMID 37479689, 2023). "To elucidate the mechanism of STAG2-deficient thyroid cancer cells being more sensitive to glutamine deprivation, we first determined the impact of STAG2 knockdown on the expression of glutamine transporter SLC1A5 and glutaminases GLS and GLS2, which are essential for glutamine metabolism." (PMID 37479689, 2023). "As a result, the mRNA levels of GLS and GDH in normal thyroid follicular epithelial cells (Nthy-ori 3–1) were lower than those in thyroid cancer cells, including PTC cell lines (TPC-1, BCPAP and K1), an FTC cell line (FTC-133), and an ATC cell line (8305C)." (PMID 38386265, 2024). "The expression of glutaminase (GLS) and glutamate dehydrogenase (GDH) in thyroid cancer tissues was evaluated by immunohistochemistry, and glutamine metabolism-related genes were assessed using real time-qPCR and western blotting." (PMID 38386265, 2024). "Glutamine metabolism-related genes, including amino acid transporter (ASCT2), amino-releasing enzymes (GLS and GDH), and aminotransferases (GPT, GOT, and PSAT1), were all up-regulated in thyroid cancer cells." (PMID 38386265, 2024). "Patients with ATC also showed the highest level of glutaminase 1 (GLS1) and glutamate dehydrogenase (GDH) compared to other thyroid cancer types." (PMID 37573361, 2023). "The majority of metabolism-related molecules, such as GLUT1 (glucose transporter 1), HK1 (hexokinase 1), LDH-A (lactate dehydrogenase A), GLS1 (glutaminase), and MCT1 (monocarboxylate transporter 1) are upregulated in different subtypes of thyroid carcinoma." (PMID 31947935, 2020). "We next investigated the expression of GLS and GDH in thyroid cancer cells in vitro." (PMID 38386265, 2024). "Our data showed that STAG2 knockdown not only made BRAF-mutant thyroid cancer cells more dependent on glutamine rather than glucose, but also rendered them more sensitive to glutaminase inhibitor." (PMID 37479689, 2023). "Mechanistically, knocking down STAG2 in BRAF-mutant thyroid cancer cells decreases the protein stability of c-Myc via the ERK/AKT/GSK3β feedback pathway, thereby impairing glutamine metabolism of thyroid cancer cells by down-regulating its downstream targets such as SCL1A5, GLS and GLS2." (PMID 37479689, 2023).
asthma (6 papers, 2015 to 2023). "Zaprinast, a phosphodiesterase 5 inhibitor and asthma drug, was recently discovered to be an inhibitor of the enzyme glutaminase (GLS)." (PMID 34359941, 2021). "Additionally, the asthma medication Zaprinast has been recently identified as a glutaminase inhibitor." (PMID 26439804, 2015). "The individuals with asthma have lower levels of ammonia in their breath than healthy individuals and also the concentrations of ammonia produced by glutaminase may be directly affected by the levels of corticosteroids and cytokines produced by asthma patients." (PMID 26854142, 2015). "Notably, while no previous reports exist of increased glutaminolysis in asthma, studies have documented increased plasma glutamine levels and altered glutaminase activity in airway epithelial cells of asthmatic patients." (PMID 26147848, 2015).
Burkitt lymphoma (6 papers, 2015 to 2021). A rare form of malignant mature B-cell non-Hodgkin lymphoma. "The HBL-1, HT, TMD8, WSU-DLCL-2 DLBCL cell lines and Karpas-422 NHL cell lines and the Raji Burkitt’s lymphoma cell line all demonstrate phenotypic sensitivity to the GLS inhibitor BPTES." (PMID 29050199, 2017).
chondrosarcoma (6 papers, 2018 to 2023). A malignant cartilaginous matrix-producing mesenchymal neoplasm arising from the bone and soft tissue. "This means that the MEK and ERK signaling pathways regulate SLC1A5 and GLS expression as well as glutamine metabolism in cisplatin-resistant chondrosarcoma." (PMID 37928274, 2023). "The pharmacological inhibition of SLC1A5 or GLS was shown to antagonize cisplatin-induced cell death in parental chondrosarcoma and SW1353-R-AR shRNA cells." (PMID 37928274, 2023). "The MEK, ERK, and NrF2 signaling pathways were shown to control AR-mediated SLC1A5 and GLS expression as well as glutamine metabolism in cisplatin-resistant chondrosarcoma." (PMID 37928274, 2023). "The MEK, ERK, and NrF2 signaling pathways were shown to regulate AR-mediated alanine-serine-cysteine transporter 2 (ASCT2; also called SLC1A5) and glutaminase (GLS) expression as well as glutamine metabolism in cisplatin-resistant chondrosarcoma." (PMID 37928274, 2023). "The further development of AR, SLC1A5 and GLS inhibitor or antibodies are potential candidates to treat of cisplatin-resistant chondrosarcoma." (PMID 37928274, 2023). "A comparative study found that compared with low-grade chondrosarcoma, the expression of glycolysis-related genes is increased, and glutaminase is also high in high-chondrosarcoma, but glutamine degradation has nothing to do with IDH1/2 mutation." (PMID 33981605, 2021). "The SW1353 chondrosarcoma cell line was particularly sensitive for inhibition of glutaminase, which is in line with the high basal GSH levels measured in this cell line." (PMID 31160965, 2019). "In conclusion, our results demonstrate that glutaminase is higher expressed in high-grade compared to low-grade chondrosarcomas." (PMID 29576625, 2018). "First, we inhibited glutaminase using the glutaminase inhibitor CB-839, and indeed, six out of ten chondrosarcoma cell lines showed IC50 values below 20 μM." (PMID 29576625, 2018). "In this study, we demonstrated a difference in glutaminase expression levels between the different chondrosarcoma grades, with the highest expression observed in high-grade tumours." (PMID 29576625, 2018). "In conclusion, these experiments demonstrate that a subset of chondrosarcoma cell lines is dependent on glutaminase-mediated glutaminolysis to maintain cell viability." (PMID 29576625, 2018). "Our research group published that the reported synthetic lethal interaction between IDH mutations and Bcl-2, NAMPT, and glutaminase inhibition was absent in chondrosarcoma." (PMID 31810230, 2019). "In cisplatin-resistant chondrosarcoma, the MEK, ERK, and NrF2 signaling pathways regulate AR-mediated SLC1A5 and GLS expression as well as glutamine metabolism." (PMID 37928274, 2023). "The knockdown of AR expression in cisplatin-resistant chondrosarcoma cells was shown to reduce the expression of SLC1A5 and GLS in vivo." (PMID 37928274, 2023). "A difference in glutaminase expression levels between the different tumour grades (p = 0.001, one-way ANOVA) was identified, with the highest expression observed in high-grade chondrosarcomas." (PMID 29576625, 2018). "Inhibition of glutaminase using CB-839 in ten chondrosarcoma cell lines revealed that HT1080 (IDH1R132C), SW1353 (IDH2R172S) and, to a lesser extent, JJ012 (IDH1R132G), were very sensitive for glutaminase inhibition, with IC50 values below 5 μM." (PMID 29576625, 2018). "We could not identify a correlation between levels of glutaminase expression and sensitivity for any of these metabolic compounds in the panel of ten chondrosarcoma cell lines." (PMID 29576625, 2018).
colorectal tumor (6 papers, 2015 to 2025). "Colorectal tumors with high glutaminase (GLS) expression exhibited reduced T cell infiltration and cytotoxicity, leading to poor clinical outcomes." (PMID 39482885, 2025).
epilepsy (6 papers, 2013 to 2024). A brain disorder characterized by episodes of abnormally increased neuronal discharge resulting in transient episodes of sensory or motor neurological dysfunction, or psychic dysfunction. "This case indicates that the phenotypic spectrum evoked by GLS hyperactivity may include epilepsy." (PMID 37151363, 2023). "Third, although GLS2 is a GLS, we did not detect the metabolic levels of glutamine or glutamic acid in epilepsy." (PMID 39404053, 2024). "However, no information is currently available regarding whether or not the expression of glutaminase in the ACC is altered in patients with epilepsy." (PMID 23531457, 2013).
head and neck squamous cell carcinoma (6 papers, 2019 to 2026). A squamous cell carcinoma that arises from any of the following anatomic sites: lip and oral cavity, nasal cavity, paranasal sinuses, pharynx, larynx, and salivary glands. "A causal relationship between glutaminase activity and ALDH levels has been proposed in head and neck squamous cell carcinoma (HNSCC)." (PMID 36768660, 2023).
HIV-1 infection (6 papers, 2012 to 2020). The type species of lentivirus and the etiologic agent of acquired immunodeficiency syndrome (AIDS). "Our previous studies have demonstrated that glutaminase is released to the extracellular fluid during HIV-1 infection and neuroinflammation." (PMID 26546362, 2015). "Treatment of MDM with IFN-α (or HIV-1 infection) has been reported to increase glutaminase (GLS1) expression through phosphorylation of STAT1, which was shown to act through GLS1 promoter." (PMID 24894206, 2014). "We posit that during HIV-1 infection and immune activation, microvesicles may mediate glutaminase release, generating excessive and neurotoxic levels of glutamate." (PMID 26546362, 2015). "Understanding GLS regulation in HIV-1 infection may further elucidate how HIV-1 induces neurotoxicity, therefore providing a new target for therapeutic intervention." (PMID 24086752, 2013). "Understanding glutaminase regulation and its effect on glutamate production in HIV-1 infection may elucidate further information on how HIV-1 infection induces neurotoxicity, ultimately helping to develop new therapies." (PMID 22479354, 2012). "Together, these data indicate that both HIV-1 infection and IFN-α treatment increase glutaminase expression through STAT1 phosphorylation and by binding to the GLS1 promoter." (PMID 22479354, 2012). "In a well-characterized model of HIV-1 infection in human MDM, we have shown that IFN-α treatment or HIV-1 infection of MDM activates STAT1 phosphorylation to bind to and upregulate the GLS1 promoter activity, and subsequently increased glutaminase and glutamate production." (PMID 22479354, 2012).
liver fibrosis (6 papers, 2020 to 2024). "In mice or patients with hepatic fibrosis, inhibition of glutaminase blocked the accumulation of MYFs and fibrosis progression." (PMID 38074679, 2023). "Glutaminase expression in experimental models of chronic liver injury is increased in liver samples from both non-alcoholic steatohepatitis and advanced liver fibrosis patients." (PMID 37513376, 2023). "The inhibition of glutaminolysis with glutaminase inhibitors or glutamine deprivation reduces the worsening of liver fibrosis." (PMID 37513376, 2023). "Indeed, in liver fibrosis induced in animal models with carbon tetrachloride pre‐treatment with a glutaminase inhibitor potently reduced liver fibrosis." (PMID 33140521, 2020). "The expression of glutaminase is enhanced in chronically injured human livers, providing further support that targeting glutaminolysis with glutaminase inhibitors (such as BPAN and CB-839) may become a successful approach for treating liver fibrosis." (PMID 33187083, 2020).
osteosarcoma (6 papers, 2020 to 2024). A usually aggressive malignant bone-forming mesenchymal neoplasm, predominantly affecting adolescents and young adults. "Targeting glutaminase activity emerges as a potential therapeutic strategy for osteosarcoma and other cancers, aiming to disrupt metabolic dependencies and hinder tumor progression." (PMID 38649439, 2024). "Highly metastatic osteosarcoma cell lines require glutamine for proliferation, and conversely, glutaminase-1 (GLS-1) inhibition limits metastatic progression in osteosarcoma." (PMID 37197432, 2023). "In a recent study, inhibition of glutamine anaplerosis with GLS-1 inhibitor CB-839 reduced the growth of primary osteosarcoma progression and metastasis progression in mouse." (PMID 35392503, 2022). "Furthermore, Glutaminase-1 (GLS-1), vital in glutamine metabolism, is indispensable for highly metastatic osteosarcoma cells." (PMID 38140058, 2023). "Glutaminase (marker of glutaminolysis) was highly expressed in 53.6% of the cases, with a median H-score of 102, suggesting that glutamine may be used as an alternative bioenergetic substrate in osteosarcoma tumorigenesis." (PMID 35392503, 2022).
renal carcinoma (6 papers, 2016 to 2025). A carcinoma arising from the epithelium of the renal parenchyma or the renal pelvis. "GPX4 and glutaminase inhibitors can inhibit pyrimidine synthesis and increase ROS levels in VHL-deficient renal carcinoma cells, and the PARP inhibitor olaparib and glutaminase inhibitors can synergistically inhibit the growth of these cells in vivo and in vitro." (PMID 39399506, 2024).
acute lymphoblastic leukemia (5 papers, 2015 to 2026). Leukemia with an acute onset, characterized by the presence of lymphoblasts in the bone marrow and the peripheral blood. "Attempts to test the effectiveness of Acinetobacter glutaminasificans glutaminase-asparaginase against acute lymphoblast leukemia in patients were discontinued due to strong side effects, presumably due to high glutaminase activity." (PMID 35335974, 2022). "Apart from that, several genes of medically useful enzymes have been found, namely, l-asparaginase, glutaminase, and RNase P. L-asparaginase and glutaminase have anticancer activity and are used to treat acute lymphoblastic leukemia." (PMID 27789644, 2016). "For this purpose, a clinical drug L-asparaginase (L-ASP), which catalyzes the hydrolysis of asparagine to aspartate and used in the treatment of acute lymphoblastic leukemia (ALL) in children, was used in this study to enzymatically deplete glutamine by its glutaminase activity." (PMID 28245869, 2017). "In conclusion, L-asparaginase showed no glutaminase activity and good stability over a wide range of physiological conditions, and thus it could be used as a potential candidate for treatment of acute lymphoblastic leukemia." (PMID 26413120, 2015).